TPH2 (tryptophan hydroxylase 2)
Synonyms: NTPH; FLJ37295; ADHD7
Tractability: Small molecule: an approved drug acts on it; a structure with a bound ligand is known; a high-quality ligand is known; it belongs to a druggable protein family. PROTAC: a small molecule that binds it is known.
Target class: Enzyme; Oxidoreductase
Gene: Protein-coding gene on chromosome 12 (71,938,845 to 72,186,618, forward strand). Ensembl gene ENSG00000139287.
Pathways (Reactome):
Metabolism: Serotonin and melatonin biosynthesis
Gene Ontology:
Molecular function: tryptophan 5-monooxygenase activity; iron ion binding; monooxygenase activity; oxidoreductase activity, acting on paired donors, with incorporation or reduction of molecular oxygen, reduced pteridine as one donor, and incorporation of one atom of oxygen
Biological process: aromatic amino acid metabolic process; serotonin biosynthetic process
Cellular component: cytosol; neuron projection
Genetic constraint (gnomAD): Loss-of-function variants: 22 observed, 57.38 expected, observed/expected ratio (o/e) 0.38, 90% interval 0.27 to 0.55. The upper end of that interval is the gene's LOEUF score, 0.55, which puts it in group 2 of 6, group 1 being the genes least tolerant of losing a copy. Missense variants: 519 observed, 616.89 expected, observed/expected ratio (o/e) 0.84, 90% interval 0.78 to 0.9. Synonymous variants: 220 observed, 223 expected, observed/expected ratio (o/e) 0.99, 90% interval 0.88 to 1.1.
Homologues: Orthologues: chimpanzee TPH2 (99% identical), macaque TPH2 (99% identical), pig TPH2 (97% identical), rabbit TPH2 (96% identical), guinea pig TPH2 (96% identical), mouse Tph2 (93% identical), rat Tph2 (93% identical), dog TPH2 (91% identical), tropical clawed frog TPH2 (80% identical), zebrafish tph2 (78% identical), Drosophila melanogaster Trhn (53% identical), Caenorhabditis elegans tph-1 (48% identical). Paralogues in human: TPH1 (65% identical), PAH (50% identical), TH (47% identical).
Diseases named in the same sentence as TPH2 in open-access papers:
TPH2 is named in the same sentence as 115 diseases in open-access papers, as found by Europe PMC text mining. Sharing a sentence is not in itself a finding about the gene and the disease. The quoted sentences say what the papers report.
depression (126 papers, 2009 to 2026). "Efavirenz (EFV), an antiretroviral agent against HIV, is associated with depression disorders and Tryptophan hydroxylase type 2 (Tph2) deregulation in mice." (PMID 42196482, 2026). "The abnormal expression of TPH2 and IDO1 has been linked to 5-HT system dysfunction and mental disorders like depression, whereas upregulating TPH2 and IDO1 enhances tryptophan metabolism, exerting antidepressant-like effects." (PMID 40290020, 2025). "Disruption or mutation of Tph2, leading to impaired serotonin synthesis, is considered a typical mechanism underlying the onset of depression." (PMID 41041075, 2025). "Second, iron complexes can be effective for correcting some depressive disorders caused by mutations in the Tph2 gene." (PMID 40943114, 2025). "In previous studies, analysis of the TPH2 gene has revealed variants associated with depression, suicide, and bipolar affective disorder." (PMID 39768746, 2024). "TPH2, the key and rate-limited enzyme of serotonin synthesis in the brain, affects the risk of depression." (PMID 39044270, 2024). "In the present study, we determined the effects of SARS-CoV-2 infection on the expression of TPH2, the rate-limiting enzyme of serotonin, which is closely associated with neuropsychiatric symptoms, such as depression, as well as its effects on nerve damage." (PMID 39475992, 2024). "A relative meta-analysis has shown that two TPH2 SNPs, rs17110747 and rs4570625, are associated with major depressive disorder." (PMID 37374342, 2023). "Another investigation exploring susceptibility variations related to suicide attempts in patients with major depressive disorder identified TPH2 as the top susceptibility gene in gene-based analyses." (PMID 38012695, 2023). "The allele A of rs11178997 affects the expression of TPH2 by inhibiting its transcriptional activity in neurons, resulting in reduced 5-HT synthesis and depression." (PMID 37161455, 2023). "Of numerous candidate TPH2 variants, TPH2 rs7305115 has been prominently linked with major depressive disorder, suicide-related behaviour, and autism spectrum disorder." (PMID 38093326, 2023). "We demonstrate that rs1386494, a common TPH2 variant previously linked to depression, suicidality, and antidepressant response, is associated with substantially altered MAO-A levels in humans in vivo." (PMID 37322010, 2023). "In terms of TPH2 functionality in humans, polymorphisms in TPH2 have also been associated with depression and anxiety." (PMID 36984895, 2023). "The functional polymorphism rs120074175, in which arginine at position 441 in the coding region of the human gene is replaced by histidine, can cause 80% loss of TPH2 function, which in turn reduces 5-HT synthesis and triggers depression." (PMID 37161455, 2023). "Genetic variants within the genes coding for the central monoamine-turnover proteins MAO-A (MAOA) and TPH2 (TPH2) have been linked to risk for depressive disorders and related phenomena." (PMID 37322010, 2023). "Other variants of the Tph2 gene were also associated with a higher incidence of anxiety disorder in women and with peripartum major depression." (PMID 35326487, 2022). "Consistently, loss-of-function mutations of TPH2 have been associated with susceptibility to major depression and suicidal behavior." (PMID 31980728, 2021). "TPH2 G703T has been linked to psychiatric disorders such as alcohol dependence, schizophrenia, and major depression, leading to serious conditions like suicidal risks." (PMID 34900485, 2021). "As the rate-limiting step of this neurotransmitter biosynthesis, mutations in TPH2 have been associated with several PD, such as bipolar disorder, depression, and attention deficit-hyperactivity disorder." (PMID 32119710, 2020). "Three genes from the list (Slc17a7, Slc6a4 and Tph2) are associated with the terms abnormal fear/anxiety-related behavior and abnormal depression-related behavior." (PMID 32917038, 2020).
depression (continued). "Functional polymorphisms of the TPH2 gene have repeatedly been found to be associated with depressive disorders, PTSD, and the personality trait harm avoidance which is negatively associated with resilience." (PMID 33052028, 2020). "Tryptophan hydroxylase 2 (the catalyst which produces serotonin, a neurotransmitter implicated in the pathogenesis of depression, from tryptophan) has been found to be modulated by 25(OH) D." (PMID 31640594, 2019). "Potential associations between TPH2 genes and poststroke depression (PSD), poststroke emotional incontinence (PSEI), and poststroke anger proneness (PSAP) were investigated 3 months poststroke." (PMID 29484259, 2018). "Genetic variation in the TPH-2 gene has recently received much attention because of its potential association with the risk of depression and sleep disturbance." (PMID 29952309, 2018). "A large number of studies have supported the association of the TPH-2 gene with central nervous system disorders, such as depression, suicidal behavior, and attention-deficit/hyperactivity disorders." (PMID 29952309, 2018). "In this study, we aimed to test the association of the TPH-2 gene polymorphism rs4290270 with primary insomnia and depression symptoms in Han Chinese." (PMID 29952309, 2018). "The influence of TPH2 expression on brain function and susceptibility to depression was supported in the transgenic animal model." (PMID 30059533, 2018). "During our experiment, we found a significant correlation between the studied TPH2 polymorphisms (rs4570625 and rs7963803) and the development of depression." (PMID 29314569, 2018). "Genetic polymorphisms of TPH2 have been demonstrated to be related to altered TPH2 expression in the central nervous system, symptoms of depression, hopelessness, cocaine addiction, and heroin addiction." (PMID 30059533, 2018). "The objective of our study was to confirm the association between the presence of polymorphic variants of TPH1 and TPH2 genes, and the development of depressive disorders." (PMID 29314569, 2018). "Although TPH-2 is often implicated in the pathophysiology of depression, few studies have applied a genetic and imaging technique to investigate the mechanism of early wakening symptom in MDD." (PMID 30519155, 2018). "Single nucleotide polymorphisms of the 5-HT1A receptor and TPH2 have been suggested to interact with the severity of depression and respond to SSRIs." (PMID 28824410, 2017). "Genetic variations of tryptophan hydroxylase 2 (TPH2) are also associated with major depression, and are further found to be associated with TPH2 mRNA expression in the pons including the DRN." (PMID 28824410, 2017). "TPH2 variation has been linked to common affective disorders such as major depression in a recent meta-analysis and is predictive of amygdala responses to emotional content." (PMID 27695066, 2016). "Tryptophan hydroxylase 2 (TPH2) catalyses the initial and rate‐limiting step in the biosynthesis of serotonin, which is associated with a variety of disorders such as depression, obsessive compulsive disorder, and schizophrenia." (PMID 27761358, 2016). "Gene-disease association studies have reported a relationship between TPH2 and major depressive disorder (MDD) in different populations, however subsequent studies have produced contradictory results." (PMID 22693556, 2012). "A large number of psychiatric illnesses have been associated with polymorphisms in the TPH2 gene to include depression, anxiety and obsessive-compulsive disorder." (PMID 23139830, 2012). "Previous studies found that mutations on the TPH2 locus in humans were associated with depression and studies of mice and studies of rhesus macaques have shown that the TPH2 locus was involved with aggressive behavior." (PMID 21765945, 2011). "A loss of function mutation (R441H) in human TPH2 was identified in patients with major depression and a loss-of-function mutation (P447R) in mice was associated with significantly reduced aggressive behavior." (PMID 21765945, 2011).
depression (continued). "Several studies have indicated possible associations between various TPH2 polymorphisms and major depression, suicidal behavior." (PMID 20738857, 2010). "A loss-of-function mutation (G1463A) in tryptophan hydroxylase-2 (TPH2), for example, the rate-limiting enzyme in 5-HT synthesis, has been identified as a factor in unipolar major depression." (PMID 19323847, 2009). "Another study showed that polymorphisms in transcription factor binding sites (TFBs), such as the TPH2 rs34517220 polymorphism, were significantly associated with improved symptoms of depression in children (mean age: 14.7 years) following Fluoxetine treatment." (PMID 41009999, 2025). "Genome‐wide studies have identified candidate genes and pathways linked to PPD, focusing on those associated with major depressive disorder like serotonin transporter, Tryptophan hydroxylase 2 (TPH2), Catechol‐O‐Methyltransferase, Monoamine oxidase, and Brain‐derived neurotrophic factor (BDNF)." (PMID 40041772, 2025). "Although the impact of TPH2 SNPs in terms of depression in PWH was evaluated, showing a higher risk of severe depression in carriers of the rs4570625 TT and rs1386493 GG polymorphic variants, the sample was small, and the cohort will need to be expanded to clarify this result." (PMID 39768746, 2024). "Depressive disorders have been associated with the Tryptophan hydroxylase type 2 (TPH2) gene." (PMID 39768746, 2024). "Similarly, the common TPH2 SNPs rs1386494 (T/C, intronic) and rs4570625 (T/G, promotor) are among those within this gene most decisively linked to depression." (PMID 37322010, 2023). "A study based on three–way interaction among the TPH2 rs7305115, the serotonin transporter gene and childhood abuse found that the serotonin transporter gene was associated with increased depression scores after childhood abuse only in TPH2 G carriers genotype other than AA genotype." (PMID 38093326, 2023). "One previous study on depression revealed that among those with major depressive disorder, G carriers of TPH2 rs7305115 might be at a higher risk for suicide attempts than A homozygotes." (PMID 38093326, 2023). "Interestingly, TPH2 was recently isolated as a top susceptibility gene on suicidality in depression." (PMID 37322010, 2023). "Given that depression and abnormal aggression are often comorbid, altered expression of Zbtb20 might underlie the behavioral abnormalities reported in stressed Tph2+/− animals." (PMID 37542675, 2023). "Currently, TPH2 gene polymorphisms have been extensively studied as potential predisposing factors for mental illnesses such as major affective disorder, and major depressive disorder." (PMID 37161455, 2023). "TPH2 principally determines central 5-HT production and homeostasis, while its dysfunction has been implicated in many neuropsychiatric disorders, including depression." (PMID 37914710, 2023). "Possibly some other polymorphisms, such as FKBP5 rs1360780, rs3800373, and TPH2 G-703T, might also serve as predictors of increased depression risk." (PMID 34590201, 2023). "The tryptophan-serotonin deficiency hypothesis of aggression has been evidenced in patients with depression and a naturalistic 5-HT deficient animal model, the tryptophan hydroxylase 2 knockin mouse." (PMID 35744601, 2022). "As revealed in a systematic review, estradiol may play a role in depression by regulating the expression of genes that are associated with 5HT neurotransmissions, such as TPH-2, MAO-A and-B, SERT, and 5-HT1A." (PMID 36353576, 2022). "Moreover, G-to-A editing led to a missense variant p.R441H in TPH2 with decreased its enzyme activity, which had been associated with major depression disorder." (PMID 34093668, 2021). "In addition, different TPH2 polymorphisms have been linked to suicidal behavior and depressive disorders, and haplotype analysis of the TPH2 gene has revealed evidence of variants associated with depression, suicide, and bipolar affective disorder." (PMID 34625528, 2021).
depression (continued). "Moreover, polymorphisms in TPH2 are associated with addictive behaviors and depression in PD patients." (PMID 32858884, 2020). "In summary, the c.804‐7C>A, c.‐1668T>A, c.803+221C>A and c.‐173A>T polymorphisms of the TPH1 gene and the c.‐1449C>A, c.‐844G>T polymorphism of the TPH2 gene may be associated with depression in the Polish population." (PMID 29314569, 2018). "Clinical studies confirm that there is a connection between TPH2 genetic polymorphisms and depression and suggest that elevated TPH2 expression and activity may be a biomarker or endophenotype of depression." (PMID 30533439, 2018). "Additionally, the increased risk of DD occurrence was associated with the T/T‐C/A combined genotype of c.‐173A>T—TPH1 and c.‐1449C>A—TPH2 (rs10488682 versus rs7963803); however, the T/A‐C/C genotype decreased the risk depression occurrence." (PMID 29314569, 2018). "In addition, the G/G genotype and G allele of c.‐844G>T—TPH2 (rs4570625) were positively correlated with depression, whereas the G/T heterozygote and T allele of the same SNP were negatively correlated with the disease." (PMID 29314569, 2018). "However, the T/T homozygote of c.‐1668T>A—TPH1, the G/T heterozygote and T allele of c.‐844G>T—TPH2, and the C/C homozygote and C allele of c.‐1449C>A—TPH2 decreased the risk of development of depressive disorders." (PMID 29314569, 2018). "However, a few studies have examined which TPH2 gene variant is tightly associated with the aetiology of depression." (PMID 28968985, 2017). "Of note, tryptophan hydroxylase-2 (TpH2), a brain-specific isoform of the rate-limiting enzyme for 5-HT biosynthesis, has been implicated in the regulation of cognition, anxiety, and depression." (PMID 28008302, 2016). "Also, TPH-2 was found to be associated with major depression and pathogenesis of depression in Chinese females and suicidal behavior." (PMID 27871272, 2016). "More particularly, the results suggest that the association between the SNP of the TPH2 gene and tendency to SB in major depression might be distinct from the heritability of mood disorders." (PMID 27721799, 2016). "Clinical and experimental studies suggested the association of depression with Tph2 deficiency." (PMID 25346938, 2014). "Subsequently, endogenous depression may be caused by TPH1 dysfunction combined with compensatory TPH2 activation." (PMID 25540092, 2014). "It is possible that hypofunctional 5-HTP cells (reflecting TPH1 dysfunction) in the periphery, leading to deficient 5-HTP, low 5-HT, and concomitant compensatory TPH2 activation in the brain, may cause endogenous depression." (PMID 25540092, 2014). "The TPH2 C2755A polymorphism may represent a population-specific risk factor for peripartum major depression and anxiety disorder, perhaps by interacting with hormones in Chinese." (PMID 20738857, 2010). "TPH2 is the rate-limiting enzyme in the synthesis of serotonin in the brain, and genetic variations in the TPH2 gene have been associated with altered serotonin production and an increased risk of psychiatric disorders such as major depressive disorder and bipolar disorder." (PMID 40806257, 2025). "Hence, Sim1-mediated TPH2 regulation might represent at least one of the underlying mechanisms of the effects of TPH2 genetic variations in the depression related to PD." (PMID 37374342, 2023). "It will remain for the future to study the feasibility of using the approach followed in this work for the treatment of psychiatric patients showing TPH2 polymorphisms associated with depression and suicide attempts in who a decreased 5-HT synthesis may be involved." (PMID 34625528, 2021). "Alternatively, TPH2 may be associated with depression through other mechanisms." (PMID 29484259, 2018).